ZNF785 (zinc finger protein 785)
Description:
May be involved in transcriptional regulation.
Synonyms: FLJ32130
Tractability: No criterion of Open Targets' tractability assessment is met for any kind of drug.
Gene: Protein-coding gene on chromosome 16 (30,573,740 to 30,585,806, reverse strand). Ensembl gene ENSG00000197162.
Subcellular location: Nucleus
Subcellular location (Human Protein Atlas): Cytosol
Pathways (Reactome):
Gene expression (Transcription): Generic Transcription Pathway
Gene Ontology:
Molecular function: protein binding; DNA-binding transcription factor activity, RNA polymerase II-specific; RNA polymerase II transcription regulatory region sequence-specific DNA binding
Biological process: regulation of transcription by RNA polymerase II; regulation of DNA-templated transcription
Cellular component: nucleus
Genetic constraint (gnomAD): Loss-of-function variants: 15 observed, 10.28 expected, observed/expected ratio (o/e) 1.46, 90% interval 0.96 to 1.91. The upper end of that interval is the gene's LOEUF score, 1.91, which puts it in group 6 of 6, group 1 being the genes least tolerant of losing a copy. Missense variants: 572 observed, 558.98 expected, observed/expected ratio (o/e) 1.02, 90% interval 0.95 to 1.1. Synonymous variants: 221 observed, 225.69 expected, observed/expected ratio (o/e) 0.98, 90% interval 0.88 to 1.1.
Homologues: Orthologues: chimpanzee ZNF785 (99% identical), dog ZNF785 (56% identical), zebrafish znf646 (23% identical), zebrafish si:dkey-89b17.4 (22% identical), Drosophila melanogaster CG18011 (19% identical), Drosophila melanogaster CG1602 (18% identical), Drosophila melanogaster az2 (17% identical), zebrafish znf576.1 (16% identical), Drosophila melanogaster CG2129 (16% identical), Drosophila melanogaster CG12942 (15% identical), Drosophila melanogaster CG30020 (15% identical), zebrafish si:ch211-148l7.4 (15% identical), and 5 more. Paralogues in human: ZNF689 (51% identical), ZNF764 (44% identical), ZNF688 (37% identical), ZNF747 (33% identical), ZNF420 (31% identical), ZNF84 (31% identical), ZNF160 (30% identical), ZNF574 (29% identical), ZFP92 (28% identical), ZNF91 (28% identical), ZNF594 (27% identical), ZBTB24 (27% identical), and 24 more.